FSTL1 (follistatin like 1)
Diseases named in the same sentence as FSTL1 in open-access papers (continued):
Sharing a sentence is not in itself a finding about the gene and the disease.
cardiac hypertrophy (11 papers, 2016 to 2025). "Cardiac myocyte-derived FSTL1 serves cardioprotective functions in myocardial hypertrophy 15, but cardiac fibroblast-derived FSTL1 promotes cardiac fibroblast activation." (PMID 39990230, 2025). "Cardiac myocyte‐specific FSTL1 knockout decreases circulating FSTL1 levels in a transverse aortic constriction‐induced cardiac hypertrophy mouse model." (PMID 35585770, 2022). "In a previous study, FSTL1 stimulated angiogenesis in smooth muscles under hypoxic conditions and increased cardiac hypertrophy." (PMID 36012380, 2022). "FSTL1 also inhibited pressure overload-induced cardiac hypertrophy in mice." (PMID 32831995, 2020). "All these findings indicate that FSTL1 may become a therapeutic target for cardiac hypertrophy or other heart diseases." (PMID 29744364, 2018). "In an ischemia/reperfusion-induced myocardial injury model, systemic or intracoronary injection of FSTL1 reduced the expression of inflammatory cytokines such as TNF-α and IL-6, thereby improving cardiac hypertrophy and dysfunction." (PMID 33936382, 2021). "Specific disruption of cardiac Fstl1 gene led to exacerbated cardiac hypertrophy and left ventricular dysfunction after thoracic aortic constriction (TAC) injury, indicating that Fstl1 functions as a negative regulator of cardiac growth under stress conditions." (PMID 27799944, 2016). "The use of the human FSTL-1 (Follistatin-related protein 1) modRNA, chemically modified at the level of N-glycosylation sites, was shown to increase the proliferation of neonatal and adult MI cardiomyocytes, without triggering cardiac hypertrophy." (PMID 34685492, 2021).
diabetes (11 papers, 2011 to 2026). "After adjusting for age, sex, smoking status, drinking status, body mass index, systolic and diastolic blood pressure, heart rate, LDL, HDL, hypertension, and diabetes, plasma FSTL1 levels remained significantly associated with AAA after adjustment (OR 0.94, 95% CI 0.90–0.96, P < 0.001)." (PMID 41068431, 2025). "Sixth, we performed stepwise regression analysis, including FSTL1, age, sex, hypertension, dyslipidemia, diabetes, current smoking, and NT-proBNP in the 214 patients." (PMID 31034503, 2019). "In the diabetic sternohyoid, three of the five calcium channel genes with decreased expression (Fstl1, Atp2b3, Eef2k, Gpd2, Myl6b) were decreased in previous diabetes studies." (PMID 24199937, 2013). "In the setting of diabetes or metabolic syndrome, factors like insulin resistance, chronic low-grade inflammation, and oxidative stress may change baseline FSTL1 levels and even the direction of its downstream effects." (PMID 41602834, 2026). "This study expands the current knowledge of the protective effects of FSTL1 in cardiovascular disease and may have potential clinical relevance against MI injury in diabetes." (PMID 34957094, 2021). "In a diabetic MI model, AAV9-mediated cardiac-specific FSTL1 expression significantly reduced apoptosis and fibrosis, underscoring both the therapeutic potential and the need for context-dependent modulation." (PMID 41602834, 2026). "Finally, mechanical overload, persistent inflammation, and metabolic disturbances (e.g., diabetes) can reshape the myocardial milieu and may reprogram FSTL1 downstream signaling, thereby accelerating the transition from protective repair to pathological remodeling." (PMID 41602834, 2026).
glioma (9 papers, 2009 to 2025). A benign or malignant brain and spinal cord tumor that arises from glial cells (astrocytes, oligodendrocytes, ependymal cells). "Higher expressions of CER1 and FSTL1 were associated with poor survival and early glioma recurrence." (PMID 38672212, 2024). "Fstl1, a member of the family, is elevated in high‐grade gliomas and contributes to tumor growth via the BMP4/Smad1/5/8 pathway." (PMID 40781854, 2025). "Glioma stem cells secrete Follistatin-like 1(FSTL-1), which sustains stemness and induces M2 polarization via TLR2-mediated PI3K-AKT signaling, highlighting tumor-stroma crosstalk in immunosuppression." (PMID 41488672, 2025). "Our study also showed that the expression of genes associated with poor prognosis in gliomas, such as FSTL1 and CER1, was significantly higher in grade III than in grade II gliomas." (PMID 38672212, 2024). "Jin and colleagues reported the high expression of FSTL1 in high-grade gliomas, and it facilitates glioma growth by negatively regulating the BMP4-Smad signaling." (PMID 36756161, 2023). "We identified linear associations between the expression of the DKK3, CTNNB1, FSTL1, and CSNK1A1 genes classified by the WHO glioma grade." (PMID 37149563, 2023). "The expression of four genes (CER1, FRAT1, FSTL1, and RPSA) involved in the Wnt/β-catenin pathway was significantly associated with mortality and disease progression in patients with glioma, especially in those with grade III glioma." (PMID 38672212, 2024). "Our studies detected five proteins that interacted with Fstl1 in glioma using Co-IP and pulldown experiments, i.e., DIP2A, CD14, BMP4, ActR-IIB, and follistatin, and the mRNA levels of MGMT were only increased in GBM cells transfected with DIP2A-specific siRNA (siDIP2A)." (PMID 30542120, 2019). "Therefore, FSTL1 overexpression may induce the differentiation of glioma cells into undifferentiated glioma stem-like cells, resulting in higher mortality and rapid disease progression in patients with glioma." (PMID 38672212, 2024). "Overexpression of FSTL1 has been identified as an indicator of an unfavorable prognosis in GBM patients, with research indicating that Fstl1 stimulates glioma growth via the BMP4/Smad1/5/8 signaling pathway." (PMID 40781854, 2025). "Therefore, we believe that similarly to FSTL1, CER1 may also inhibit the activation of the BMP2 pathway, which would induce undifferentiation of glioma cells and cause poor prognosis in patients with glioma." (PMID 38672212, 2024). "When the study patients were classified according to the WHO grade, CER1 and FSTL1 showed significantly higher expression, while FRAT1 showed significantly lower expression in patients with grade III glioma than in patients with grade II glioma." (PMID 38672212, 2024). "We calculated the correlations between the expressions levels of the DKK3, CTNNB1, FSTL1, and CSNK1A1 genes and eight immune cell fractions in grade II or III glioma and GBM." (PMID 37149563, 2023). "We also observed that as the grade of glioma increased, DKK3 expression showed a tendency to be more strongly positively correlated with the expression of CTNNB1, FSTL1, and CSNK1A1, which are related to the Wnt/β-catenin pathway." (PMID 37149563, 2023). "Conversely, the first FSTL1 tertile showed significantly greater OS and PFS rates than the second and third tertiles only among patients with grade II or III glioma." (PMID 37149563, 2023). "On the other hand, when the relationships between CSNK1A1 and CTNNB1 and between FSTL1 and CTNNB1 were estimated, positive correlations with similar slopes were shown in both grade II or III glioma and GBM." (PMID 37149563, 2023). "When determining the relationships among DKK3, FSTL1 and CTNNB1, we observed that the higher the grade of glioma was, the stronger the positive correlations between DKK3 and FSTL1 and between DKK3 and CTNNB1." (PMID 37149563, 2023).
glioma (continued). "Two groups independently discovered FSTL1 and named it (I) transforming growth factor (TFG)-β-induced clone 36 (TSC36) isolated from mouse osteoblasts and (II) Follistatin-related protein (FRP) secreted from rat glioma." (PMID 29594389, 2018). "Based on our findings, we hypothesized that the effects of FSTL1 and CER1 in grade III gliomas are stronger, whereas those of FRAT1 and BMP2 are weaker." (PMID 38672212, 2024). "In contrast, if the actions of FRAT1 and BMP2 become stronger and those of FSTL1 and CER1 become weaker in patients with grade III gliomas, the difference in survival and disease progression between these opposing groups may significantly increase." (PMID 38672212, 2024). "However, when the relationship between FSTL1 and CSNK1A1 was estimated, the positive correlation between FSTL1 and CSNK1A1 was stronger in GBM than in grade II or III glioma." (PMID 37149563, 2023). "Based on previously published studies and our current findings, we herein present schematic illustrations of the hypothetical role of DKK3 in glioma progression considering its interaction with CTNNB1, FSTL1, and CSNK1A1, which are involved in the Wnt/β-catenin signaling pathway." (PMID 37149563, 2023). "Interestingly, there were Wnt/β-catenin-related genes whose mRNA expression levels were noticeably increased in GBM compared with grade II and III glioma, and those genes were catenin beta 1 (CTNNB1), follistatin-like 1 (FSTL1), and casein kinase 1 alpha 1 (CSNK1A1)." (PMID 37149563, 2023). "FSTL1 is not expressed at a detectable level in normal brain tissue and in diffuse-infiltrating astrocytes of grade II or III gliomas, but is expressed at high levels in grade IV gliomas, referred to as glioblastoma." (PMID 29594389, 2018).
hepatocellular carcinoma (9 papers, 2018 to 2024). A malignant tumor that arises from hepatocytes. "Additionally, activated tumor-associated fibroblasts have been identified as secretors of FSTL1, influencing hepatocellular carcinoma cells to augment metastasis and stemness, thereby contributing to disease progression." (PMID 38605354, 2024). "For example, FSTL1 has been found to be reduced in a variety of cancer types, including prostate and kidney cancers, but elevated in brain tumors and hepatocellular carcinoma." (PMID 35450397, 2022). "A previous study observed that FSTL1 was expressed in fibroblasts and correlated with metastasis of hepatocellular carcinoma but was barely detectable in cancer cell lines." (PMID 35450397, 2022). "In the present study, we observed that the expression of FSTL1 was increased in the HBV-infected hepatoma cell lines as compared with those in the normal hepatoma cell lines." (PMID 32188476, 2020). "Overexpression of FSTL1 in a human hepatocellular carcinoma (Huh7) cell line promoted its expansion, being the result of increased proliferation and inhibited apoptosis." (PMID 29594389, 2018). "Interestingly, a preceding study has uncovered that FSTL1 aggravates hepatocellular carcinoma progression via inducing AKT/GSK-3β pathway activation." (PMID 34555811, 2021). "Similarly, the level of miR-1287-5p was decreased and the protein level of FSTL1 was increased in the HBV-infected hepatoma cell lines as compared with those in the normal hepatoma cell lines." (PMID 32188476, 2020). "However, the mRNA levels of FSTL1 were significantly increased in the HBV-infected hepatoma cells as compared with those in the normal hepatoma cells." (PMID 32188476, 2020). "For instance, FSTL1 can bind to TLR4, activating AKT/mTOR/4EBP1 signaling and enhancing hepatocellular carcinoma metastasis and stemness." (PMID 38605354, 2024). "Serum concentrations of FSTL1 levels were determined for healthy controls (CTL) and patients with viral hepatitis B (HBV), cirrhosis (LC) and hepatocellular carcinoma (HCC)." (PMID 32933544, 2020). "Contrarily, increased expression of FSTL1 as opposed to healthy tissue was observed in brain cancer, castration-resistant prostate cancer, in most cases of hepatocellular carcinoma (HCC), squamous cell carcinoma of the head, neck, and esophagus." (PMID 34440203, 2021).
ischemia (9 papers, 2018 to 2026). A hypoperfusion of the BLOOD through an organ or tissue caused by a PATHOLOGIC CONSTRICTION or obstruction of its BLOOD VESSELS, or an absence of BLOOD CIRCULATION. "Recent studies suggest that FSTL1 is secreted as a response to injuries caused by ischemia, and overexpression of FSTL1 can protect the heart and blood vessels." (PMID 38058391, 2023). "On the other hand, the severity of ischemia and the time window being studied can also define where the “benefit vs harm” boundary falls for FSTL1 signaling." (PMID 41602834, 2026). "FSTL1 is a secreted factor from skeletal muscle; it participates in revascularization during ischemia and is related to the function of angiogenesis in skeletal muscle." (PMID 39281413, 2024). "Experimental studies demonstrate that intramyocardial delivery of modRNA encoding non-glycosylated follistatin-like 1 (Fstl1) and pyruvate kinase muscle isozyme 2 (Pkm2) promotes cardiac proliferation and regeneration in murine ischemia models." (PMID 41515935, 2025). "Follistatin-like 1 (FSTL1), also known as transforming growth factor β-stimulated clone 36 (TSC-36), has been identified as a cardioprotective factor that could protect cardiomyocytes and decrease apoptosis induced by ischemia/reperfusion (IR) injury." (PMID 29744364, 2018).
acute coronary syndrome (8 papers, 2011 to 2020). Signs and symptoms related to acute ischemia of the myocardium secondary to coronary artery disease. "Clinical studies showed that circulating Fstl1 levels are elevated in association with acute coronary syndrome and chronic heart failure." (PMID 27145224, 2016). "Previous studies showed that serum FSTL1 concentrations were increased in acute coronary syndrome and chronic heart failure." (PMID 31034503, 2019). "Previous clinical studies showed that serum FSTL1 concentrations were increased in patients with acute coronary syndrome (ACS) and chronic systolic heart failure (HF)." (PMID 31034503, 2019). "Clinically, circulating levels of Fstl1 are elevated in patients with acute coronary syndrome." (PMID 27145224, 2016). "Although the effects of FSTL1 on inflammation and immunity are complex and controversial, serum FSTL1 concentrations have been assessed in healthy individuals and patients with acute coronary syndrome (ACS), and shown to relate to ACS mortality during follow-up." (PMID 22117761, 2011). "Circulating levels of FSTL1 may work as a biomarker as high concentrations of FSTL1 are seen in patients with systolic and diastolic heart failure, and as FSTL1 levels exhibit prognostic significance in the acute coronary syndrome." (PMID 32393961, 2020). "Recent findings also suggested that the secreted protein FSTL-1 could be an upstream inducer of GDF15 production and an independent prognostic biomarker in acute coronary syndromes." (PMID 25171167, 2014).
asthma (8 papers, 2013 to 2024). "We then aimed to analyze the association between FSTL1 and a series of clinical parameters to help identify mechanisms behind the pathology of airway remodeling in asthma." (PMID 28845090, 2017). "Whether airway remodeling in asthma is halted or slowed or if the decline of FSTL1 is linked with the improvement of pulmonary function, testing is still not clear and requires further investigation." (PMID 28845090, 2017). "Proteomic analysis of the sputum of patients with asthma also displayed that FSTL1 is one of the most abundantly expressed proteins." (PMID 36290379, 2022). "Histological analysis of post-mortem human lungs of asthma patients showed expression of FSTL1 in alveolar macrophages." (PMID 29594389, 2018). "Proteomic analysis of sputum of patients with asthma revealed that FSTL1 is one of the highest expressed proteins." (PMID 29594389, 2018). "Of note, plasma concentrations of FSTL1 in the asthma group (130.762 ± 46.029 ng/mL) were significantly elevated compared to controls (95.408 ± 33.938 ng/mL) (p = 0.009)." (PMID 28845090, 2017). "Investigation of molecular mechanisms was outside the scope of our study, but taking previous work in the literature into consideration, we believe that FSTL1 is likely to promote airway remodeling in asthma." (PMID 28845090, 2017). "Our findings here add new insights into the understanding of asthma and indicate a potential novel role of FSTL1 in asthma." (PMID 28845090, 2017). "Follistatin-like 1 (FSTL1)-induced autophagy may promote epithelial–mesenchymal transition, suggesting its potential for new asthma treatments." (PMID 38891935, 2024). "In contrast, other trials demonstrated FSTL1′s important role as a pro-inflammatory cytokine in the pathogenesis of bronchial asthma, promoting airway remodeling and airway inflammation in patients with asthma." (PMID 36290379, 2022). "Moreover, the elevated levels of FSTL1 were found in blood plasma and bronchoalveolar lavage fluid in asthma patients compared to healthy controls." (PMID 29594389, 2018). "Since elevated levels of FSTL1 coexist with airway remodeling in asthma, we wonder whether FSTL1 participates in airway remodeling as a mediator or whether FSTL1 levels increase following airway remodeling as a kind of maladaption." (PMID 28845090, 2017). "Moreover, after treatment for asthma, the levels of FSTL1 in plasma declined, but due to moral and ethical reasons, we were unable to assess airway remodeling with additional bronchoscopy procedures." (PMID 28845090, 2017). "Dexamethasone, which is a glucocorticoid used to treat both asthma and COPD, is associated with expression of both KCNS3 and FSTL1; interestingly, there are striking similarities in the effects of dexamethasone and 1,25-dihydroxyvitamin on the expression of these genes." (PMID 24274704, 2013). "There was an association between FSTL1 and airway remodeling in asthmatics without treatment suggesting that it may promote airway remodeling in people with asthma." (PMID 28845090, 2017). "Recent studies suggest that FSTL1 may participate in the pathogenesis of asthma." (PMID 28845090, 2017). "In summary, our study demonstrated that the levels of plasma FSTL1 were elevated in asthmatics and the levels of FSTL1 in plasma and BALF were positively correlated in people with asthma." (PMID 28845090, 2017). "Our previous study has shown that FSTL1 may promote EMT and airway remodeling in asthma by activating autophagy." (PMID 33509151, 2021). "FSTL1 was demonstrated to induce EMT and airway remodeling by activating autophagy in asthma." (PMID 33425768, 2020). "Considering that plasma FSTL1 levels fluctuate and decrease with asthma treatment and the specificity of BALF FSTL1 concentrations with remodeling parameters, we speculate that FSTL1 may play an important role in airway remodeling." (PMID 28845090, 2017).
asthma (continued). "The increased expression of FSTL1 in biopsies was accompanied by more expression of α-SMA collagen I and a thicker reticular basement membrane, which are all the hallmarks of airway remodeling in asthma." (PMID 28845090, 2017). "Moreover, FSTL1 can induce EMT and airway remodeling in asthma." (PMID 33509151, 2021). "Here, we aimed to compare the concentration of FSTL1 in plasma and bronchoalveolar lavage fluid (BALF) in patients with and without asthma." (PMID 28845090, 2017).
ovarian carcinoma (8 papers, 2016 to 2025). A malignant neoplasm originating from the surface ovarian epithelium. "Overexpression of FSTL1 was associated with poor prognosis of glioblastoma and favored the progression of prostate cancer; its inactivation in colon, stomach, breast, kidney, lung, endometrial and ovarian cancers suggests a function as a putative tumor suppressor gene." (PMID 26918942, 2016). "FSTL1 is downregulated in ovarian cancer, endometrioid cancer, and kidney carcinoma, and a decrease in FSTL1 is related to a poor prognosis." (PMID 35805015, 2022). "In other studies, FSTL1 has been demonstrated to induce apoptosis and inhibit invasion and metastasis in endometrial carcinoma and ovarian carcinoma." (PMID 33639614, 2021). "In endometrial cancer and ovarian cancer, FSTL1 also has a tumor suppressive function to regulate cell proliferation, apoptosis, invasion and migration." (PMID 28852126, 2017). "In ovarian cancer, restored FSTL1 expression could inhibit tumor cell migration by reducing the secretion of matrix metalloproteinase 2 (MMP2)." (PMID 26918942, 2016). "When FSTL1 and RAD51AP1 genes were silenced in ovarian cancer cells, a decrease in proliferation was noted while the Bax gene expression remained unchanged." (PMID 31338320, 2019).